HSF1 (heat shock transcription factor 1)
Diseases named in the same sentence as HSF1 in open-access papers (continued):
Sharing a sentence is not in itself a finding about the gene and the disease.
melanoma (continued). "HSF1 depletion markedly lowered the tumorigenic potential of melanoma cells in nude mice." (PMID 35311075, 2022). "Interestingly, the suppression of HSF1 appears to exert anti-proliferative effects in melanoma cells under hyperthermic conditions." (PMID 30013176, 2018). "In melanoma cells Fbxw7 abundance is decreased, resulting in increased HSF1 protein levels." (PMID 28194040, 2017). "HSF1 was found among six metastasis-promoting genes in malignant melanoma cells." (PMID 24467529, 2014). "The obtained results suggest that HSF1 overexpression may contribute to the generation of SP phenotype of melanoma cells." (PMID 24165036, 2013). "To determine whether the elevated expression of HSF1 could affect cell response to cytotoxic drugs we established mouse (B16F10) and human (WM793B and 1205Lu) melanoma cells overexpressing the full form of the human HSF1 (hHSF1)." (PMID 24165036, 2013). "We also obtained mouse melanoma B16F10 cells with a silenced HSF1 expression." (PMID 24165036, 2013). "Surprisingly, we revealed that such selective resistance of melanoma cells was not dependent on direct transcriptional activity of HSF1 (and linked HSPs expression and accumulation)." (PMID 24165036, 2013). "Furthermore, HSF1 phosphorylation has an impact on melanoma cell proliferation." (PMID 35906200, 2022). "Increased amyloidogenesis by MEK or HSF1 inhibition blunted melanoma growth, by exacerbating proteotoxic stress to a lethal threshold, thus suggesting that the induction of proteotoxic stress might have relevant anti-melanoma effects and represent a promising therapeutic strategy." (PMID 27896217, 2016). "We have concluded that HSF1-associated resistance of melanoma cells treated with doxorubicin or paclitaxel was not coupled to HSPs expression, as cells overexpressing the transcriptionally active form of HSF1 did not acquire resistance to these drugs despite elevated level of HSPs." (PMID 24165036, 2013). "In these, HSF1 gene knockdowns resulted in impaired growth rates, reduced invasion and metastatic capabilities of xenografted HCC and melanoma cells in immunocompromised mice." (PMID 40287736, 2025). "Our observations suggest that the phosphorylation-mediated HSF1 complexes including the TRRAP–TIP60 complex and the TRIM33–TRIM24 proteins are therapeutic targets for the treatment of melanoma patients." (PMID 35906200, 2022). "Using an in silico cohort of IFN-treated melanoma tissues, we validated a differentially expressed 9-gene core of DEGs, out of which four genes had a predictive power for efficacy: WFDC1, HSPB7, HSF1, and MT2A." (PMID 35269844, 2022). "Without FBXW7, HSF1 accumulates and activates the metastatic pathway of melanoma, driving cancer survival and metastasis." (PMID 39433125, 2024). "Interestingly, a recent study showed that upon cellular stress HSF1 physically interacts with and is directly phosphorylated by MEK, a pivotal kinase of the MAPK pathway, and as a consequence promotes melanoma growth." (PMID 27896217, 2016). "The expression of constitutively active mutant HSF1, also resulting in HSPs overproduction, did not reduce the sensitivity of melanoma cells to drugs, unlike in the case of dominant negative form expression." (PMID 24165036, 2013). "We also compared the gene profile between melanoma cells treated with HSP90 inhibitor with or without HSF1 knockdown." (PMID 23615731, 2013). "Hence, overexpression of the human HSF1 was sufficient to activate some HSP genes in mouse and human melanoma cells in heat shock-independent manner." (PMID 24165036, 2013).
colorectal cancer (30 papers, 2015 to 2025). A primary or metastatic malignant neoplasm that affects the colon or rectum. "Hsf1 is the master regulator of the heat shock response and our findings argue that APC mutants associated with human colorectal cancer activate Hsf1." (PMID 26320184, 2015). "For example, the interaction between piR-823 and heat-shock factor 1 (HSF1) has been demonstrated to facilitate HSF1 activation and Ser326 phosphorylation, resulting in increased colorectal cancer cell proliferation." (PMID 39827178, 2025). "HSF1 activation increases DNA damage repair, contributing to radiation resistance and promoting cancer cell survival under treatment stress in colorectal cancer." (PMID 39850800, 2024). "Biochemical inhibition or siRNA silencing of HSF1 increased benzimidazole carbamate drug potency in colorectal cancer cells." (PMID 39433125, 2024). "Further experiments found that ERK-1/2 activates HSF1 through phosphorylation of S326 and promotes chemotherapeutic resistance in colorectal cancer cells." (PMID 39433125, 2024). "HSF1 has been shown to induce miR-135b-5p overexpression, which induces protective autophagy, in colorectal cancer following oxaliplatin treatment." (PMID 39850800, 2024). "Heat Shock Factor 1 (HSF1) is an oncogene in colorectal cancer, which promotes mTOR activation and glutamine metabolism." (PMID 37127605, 2023). "It interacts with HSF1 and regulates the phosphorylation at Ser326 and then the transcriptional activity in colorectal cancer cells." (PMID 38060527, 2023). "Here, our findings uncovered a novel mechanism of HSF1 regulation of glutamine metabolism and further emphasized the importance of targeting glutamine metabolism in colorectal cancer." (PMID 36010849, 2022). "More importantly, we were the first study to integrally reveal the driving forces for HSF1 overexpression in colorectal cancer by bioinformatics and experiments, providing theoretical basis for targeting HSF1." (PMID 35006040, 2022). "In 536 colorectal cancer samples, the overall mutation rate was about 97.95% (525 out of 536) and the mutant frequency of APC was up to 75%, while the mutation rate of HSF1 was only 1%." (PMID 35006040, 2022). "Now that the translation level of HSF1 mRNA in colorectal cancer is high, we wanted to explore the certain RNA binding protein." (PMID 35006040, 2022). "Similar to NCZ treatment, PBZ showed enhanced cytotoxicity and reduced chemotherapeutic resistance through ERK1/2-dependent HSF1 in colorectal cancer cells." (PMID 36230527, 2022). "In colorectal cancer, piR-823 was reported to promote cell proliferation and tumorigenesis by upregulating phosphorylation and transcriptional activity of HSF1." (PMID 33791297, 2021). "Here the authors show that, in a model of colitis-induced colorectal cancer, HSF1 is activated in stromal fibroblasts in the early stages of inflammation, leading to extracellular matrix remodelling that sustains tumor initiation and progression." (PMID 33288768, 2020). "On the other hand, miR455-3p, similar to HSF1 inhibition as we reported recently, reduced the expression of HSF1 targets, induced the viability inhibition and apoptosis activation of colorectal cancer cells." (PMID 32838807, 2020). "In recent studies, there have been reports of increased expression of HSF1 in colorectal cancer (CRC) cells, and the depletion of the HSF1 gene knockdown has inhibited colon cancer growth both in vivo and in vitro." (PMID 32110802, 2020). "For instance, the activation of apolipoprotein L1 (APOL1) is involved in HSF-1 mediated autophagic cell death in the treatment of colorectal carcinoma using Vitexin." (PMID 33027767, 2020). "In colorectal cancer, the knockdown of HSF1 inhibited mTOR activation and glutamine metabolism while attenuating the cancer cell growth in vitro." (PMID 31878360, 2019).
colorectal cancer (continued). "piR-823 interacts with heat shock factor 1(HSF1) to promote Ser326 phosphorylation and HSF1 activation, thereby enhancing colorectal cancer (CRC) cell proliferation and suppressing cell apoptosis." (PMID 31399034, 2019). "Taken together, our study insights a probable novel association between HSF-1 and ApoL-1 was established in this study, which supports HSF-1 as a potential target of vitexin to improve treatment outcome in colorectal cancer." (PMID 29348836, 2017). "To test whether HSF1 activity elevation in the presence of monocyte-like cells could also exist in cells freshly isolated from cancer patients, we used colorectal carcinoma cells (HCC cells) isolated from untreated patients." (PMID 38280079, 2024). "In this study, we demonstrated that HSF1 could also stimulate glutamine metabolism by regulating the glutamine transporter-SLC1A5/ASCT2, further highlighting the potential of targeting HSF1 in colorectal cancer." (PMID 36010849, 2022). "Targeting the HSF1/LINC00857/ANXA11 axis may provide a valuable therapeutic strategy against colorectal cancer." (PMID 36010849, 2022). "When NCZ was treated with an inhibitor of heat shock factor (HSF) 1 or the MEK/extracellular signal-regulated kinases (ERK) pathway, it exerted higher cytotoxicity than NCZ alone, thereby lessening the chemotherapeutic resistance promoted by ERK-1/2-dependent HSF1 in colorectal cancer cells." (PMID 36230527, 2022). "Consequently, insights into the precise regulatory mechanisms of the HSF1/LINC00857/ANXA11 axis in colorectal cancer progression can further develop novel specific targeted drugs and diagnostic strategies for colorectal cancer." (PMID 36010849, 2022). "Our previous studies had verified that HSF1 is highly expressed in colorectal cancer patients." (PMID 35006040, 2022). "In addition, piR-823 downregulation suppressed cell proliferation of colorectal cancer cells by a direct modulation of the transcriptional activity of HSF1." (PMID 32357464, 2020). "Furthermore, HSF1 targets were upregulated by the potent GSK3β inhibitor LiCl in colorectal cancer cell line RKO, which had a low level of β-catenin expression." (PMID 32838807, 2020). "However, the roles and driving forces for HSF1 in colorectal cancer (CRC) are poorly understood." (PMID 35006040, 2022). "However, the roles of HSF1 in colorectal cancer are poorly understood." (PMID 35006040, 2022). "In colorectal cancer, LINC00857 is a non-coding RNA overexpressed by HSF-1 (heat shock transcription factor 1)." (PMID 36499136, 2022). "Establishing relevance to human disease, we find high activation of stromal HSF1 in CAC patients, and detect the HSF1-dependent proteomic ECM signature in human colorectal cancer." (PMID 33288768, 2020). "Colorectal cancer tissue and colorectal cancer cell lines, including HCT116, SW480, and SW620, display elevated levels of HSF1, and one of its main tumor-promoting functions is to enhance glutaminolysis." (PMID 32408596, 2020). "Furthermore, transcription factors such as Heat Shock Transcription Factor 1(HSF1) and Double-Strand-Break Repair Protein Rad21 Homolog (RAD21) play a regulatory role with HNF4α in colorectal cancer metastasis." (PMID 36249028, 2022). "Till date, the probable mechanistic action of anti-cancer activity of vitexin against colorectal cancer in the context of HSF-1 as probable target molecule has not been reported yet." (PMID 29348836, 2017).
colorectal cancer (continued). "However, in the present study, when human colorectal carcinoma HCT-116 cells were exposed to vitexin, the induction of HSF-1 downstream target proteins, such as heat shock proteins were suppressed." (PMID 29348836, 2017). "Therefore, HSF1 regulated DNMT3a/MIR137HG/MIR137 / GLS axis to raise glutaminolysis and mTOR activation and promote the process of colorectal cancer, and it is a potential therapeutic target for colorectal cancer." (PMID 37127605, 2023). "Therefore, colorectal cancer stage progression is likely to be correlated with the expression of HSF-1, which indicates that HSF-1 may be a useful biomarker for CRC prognosis and the development of novel therapeutic strategies for its treatment." (PMID 29348836, 2017). "Knock-down of HSF1 by small interfering RNAs transfecting colorectal cancer cells HCT116, the comet assay results showed that lack of a functional HSF1 was unable to arrest in the G2-phase of the cycle and reduced the capacity of double-stranded DNA break repair after exposure to ionizing radiation." (PMID 36466874, 2022).
lung carcinoma (28 papers, 2014 to 2025). "Almost a decade ago, Dr. Lindquist’s group reported that HSF1 plays a dominant role in reprogramming cancer-associated fibroblasts to support the malignancy of lung cancer by promoting the production of two key stromal signaling molecules, TGF-β and SDF1." (PMID 38280079, 2024). "In particular, overexpression of HSF1 by tumor-associated macrophages (TAM) is associated with resistance to chemotherapy in lung cancer cells and tumor xenografts." (PMID 39243039, 2024). "HSF1 overexpression is common in lung cancer and correlates with tumor angiogenesis, while HSF1 activation in early-stage lung cancer cells and stroma are associated with poor outcome." (PMID 34764257, 2021). "In the present study, we sought to explore whether enhanced resistance of A549 lung cancer cells to etoposide may be caused by monocytes, particularly by their activating effect on HSF1." (PMID 38280079, 2024). "NBAT1, a tumor suppressor gene in lung cancer, also regulated associations between HSF1 and ATG7." (PMID 37958341, 2023). "For example, Heat shock factor 1 (HSF1) down-regulated mediated ER UPR can promote cisplatin resistance in lung cancer cells." (PMID 40735463, 2025). "We generated HSF1 mutants with lysine-to-arginine substitutions at five SUMOylation sites and studied their function in H1299 lung carcinoma cells with HSF1/HSF2 knockout, which lack a functional HSR." (PMID 40617887, 2025). "For instance, we previously demonstrated that the HSF1 inhibitor CL-43 substantially sensitized colorectal and lung carcinoma cells to chemotherapy." (PMID 41365861, 2025). "Several studies have demonstrated that HSF1 facilitated metastatic progression in various tumor models, such as lung cancer, breast cancer, HCC, and melanoma." (PMID 40981348, 2025). "The 8 FRGs (ACSL3, FADS2, GLS2, HSF1, PANX1, PHKG2, VDAC2, and CDKN1A) that we selected to be associated with the diagnosis and prognosis of lung cancer have been shown to play important roles in cancer and tumor immunity." (PMID 38743344, 2024). "One of the most powerful protection system is based on heat shock proteins whose synthesis is triggered by activated Heat Shock Factor-1 (HSF1); the inhibition of the HSF1 with CL-43 sensitized A549 lung cancer cells to the anti-cancer effect of etoposide." (PMID 38280079, 2024). "Among the 20E-down-regulated genes in lung cancer cells, several of them are considered to be oncogenes, including Notch3, HSF1, mTOR, SOX12, KLF16 (Kruppel-like factor 16,), and others." (PMID 37233697, 2023). "In experiments using radioresistant lung cancer cells, a knockdown of HSF1 and administration of an HSP90 inhibitor resulted in a high level of cell apoptosis and increased cell sensitivity to radiotherapy." (PMID 37958341, 2023). "Downregulation of hsp70 by knockdown of heat shock transcription factor 1 (HSF-1) suppresses lung cancer cell growth." (PMID 37178919, 2023). "In cases of lung cancer metastasis to the brain, HSF1 plays a crucial role in supporting the survival and proliferation of metastatic cancer cells." (PMID 37958341, 2023). "Breast and lung cancer exhibit aberrant expression of HSF-1, indicating a direct correlation between the tumor’s level of malignancy and its ability to metastasize." (PMID 37120556, 2023). "Our previous data demonstrated that combining the Heat Shock Factor 1 (HSF1) knockdown with Hsp90 inhibition using NVP-AUY922 radiosensitizes H1339 human lung cancer cells by impairing the DNA double-strand break repair." (PMID 35463341, 2022). "Hsf1 was previously shown to be upregulated in CAFs in breast and lung cancers and to drive a stromal tumor-promoting transcriptional program that correlated with worse prognosis." (PMID 34169837, 2021). "In lung cancer, CAFs can also promote the activity of HSF1, which stimulates tumor progression and metastasis." (PMID 32408596, 2020).
lung carcinoma (continued). "In lung cancer, the combined approach that involves HSF-1 knockdown and HSP90 inhibitor NVP-AUY922 inhibits the expression and activation of HSP90 client protein Akt and impairs Rad51-mediated homologous recombination." (PMID 31878360, 2019). "The heat shock proteins Hsp90, Hsp70, and Hsp27 and the transcription factor heat shock factor-1 (HSF-1) are frequently overexpressed in many tumor cell types, including lung carcinoma." (PMID 31569342, 2019). "In lung cancer, the HSF1 inhibitor induced cancer cell growth arrest and apoptosis and helps to overcome cancer cell resistance to conventional anti-cancer drugs, including paclitaxel and cisplatin." (PMID 31878360, 2019). "It has been reported that IBU inhibits the expression of Hsp70 by down-regulating HSF1 in human lung cancer A549 cells." (PMID 29541415, 2018). "We detected strong MA-induced phosphorylation of HSF1 at serine 326 in lung cancer cells." (PMID 34200371, 2021). "Previously, it was reported that NZ28—an inhibitor of several transcription factors including HSF-1, SP1, and NF-kB—can increase the radiosensitivity in human lung cancer cells." (PMID 31569342, 2019). "A siRNA knock-down of HSF-1 in H1339 and EPLC-272H lung carcinoma cells resulted in a significant down-regulation of Hsp70 in the cytosol of these tumor sublines, as determined by Western blot analysis and ELISA." (PMID 26197988, 2015). "Similarly to HSF1, the expression of HSF2 has been found to be upregulated in tumor tissues from lung cancer patients." (PMID 32408596, 2020).